IL1B (interleukin 1 beta)
Diseases named in the same sentence as IL1B in open-access papers (continued):
Sharing a sentence is not in itself a finding about the gene and the disease.
emphysema (continued). "The previous studies reported that both CS and LPS directly damaged airway epithelium and activated macrophages and lymphocytes to generate proinflammatory cytokines (such as TNF-α, IL-6, IL-8, and IL-1β), which then activated neutrophils, leading to chronic bronchial inflammation and emphysema." (PMID 27524867, 2016). "Furthermore, overexpression of IL-1β caused emphysema and fibrosis in the airway walls in a murine model of COPD and IL-1β has been shown to induce endothelial to mesenchymal transformation in skin." (PMID 19857272, 2009). "In our study, one explanation for the mitigation of the emphysema was decreased levels of pro-inflammatory factors in the lungs (IL-1β and CXCL1/KC) and circulation (TNF-α, IL-1β, and IL-17A) by hUC-MSCs which may associate with the reduction of the neutrophil infiltration in emphysematous mice." (PMID 34646841, 2021). "Thus, the association between elevated IL-1β and emphysema was more pronounced in never-smokers (aOR: 4.53 [95%CI: 2.05-9.98], p<0.001) than in former (aOR: 1.29 [95%CI: 0.67-2.48], p=0.453) and current-smokers (aOR: 0.97 [95%CI: 0.37-2.54], p=0.950)." (PMID 33936110, 2021). "Furthermore, when either IL-1β and IL-18 is over expressed it leads to emphysema/COPD." (PMID 25405768, 2014). "The expression of potent inflammatory cytokines such as IL-1β and TNF-α increases with exposure to cigarette smoke and can play a key role in the development of airway inflammation and emphysema." (PMID 39591423, 2024). "Compared to the emphysema model (ELA), the ACO group was superior in expressing of IL-1β, IL-4, IL-5, IL-6, IL-13, and IFN-γ." (PMID 37511021, 2023). "A recent study found that theaflavin-3,3′-digallate attenuated emphysema in mice by suppressing necroptosis and significantly decreased the TNF-α and IL-1β levels." (PMID 36979417, 2023). "Furthermore, we are unable to determine whether the observed association between elevated plasma concentrations of TNFα and IL-1β and radiographic emphysema in PLWH is due to local inflammation in the lung or rather reflects a more general state of chronic systemic inflammation." (PMID 33936110, 2021). "We further examined the levels of mRNA expression from pro-inflammatory cytokines (IL-1β and TNF-α) and an anti-inflammatory cytokine (IL-10) in the whole lungs of an emphysema model." (PMID 34425800, 2021). "PLWH with emphysema had higher concentrations of TNFα (median (IQR): 8.2 (6.4-9.8) versus 7.1 (5.7-8.6) pg/ml, p<0.001), IL-1β (0.21 (0.1-0.4) versus 0.17 (0.1-0.3) pg/ml, p=0.004) and IL-6 (3.6 (2.6-4.9) versus 3.1 (2.0-4.3) pg/ml, p=0.023) than PLWH without." (PMID 33936110, 2021). "PPE instillation in mice is a useful model to reproduce quickly several features of human emphysema and PPE instillation increased macrophages as well as IL-6, KC, IL-1β and IL-17 levels in BALF." (PMID 27775634, 2016). "Transgenic overexpression of mature IL-1β in the lung epithelium of mice evokes a phenotype that closely resembles COPD, including inflammation, emphysema, airway fibrosis, and mucus cell metaplasia." (PMID 24312100, 2013). "Elastase administration increased BAL cellularity, histological inflammation, HO-1, IL-1β and macrophage MMP-12 expression and induced emphysema." (PMID 22849372, 2012). "Moreover, it is important to mention that IL1β plays an important role in increasing inflammation in the airways of COPD patients and animals, leading to the development of inflammation and emphysema in the lungs." (PMID 38542124, 2024). "IL-1β and TNF-α stimulate macrophage and bronchial epithelial cells to produce matrix metalloprotein-9 and extracellular matrix protein-tenascin, respectively, which are involved in the pathogenesis of emphysema." (PMID 33915841, 2021). "Importantly, the mRNA levels of IL-1β, TNF-α, IL-8, IRF-5, IL-18, IFN-γ, TGF-β, matrix metalloproteinase-9 (MMP-9), and MMP-12 were decreased in the FMT-treated emphysema group compared with the emphysema group." (PMID 32681029, 2020).
emphysema (continued). "PM significantly increased mice emphysema and airway inflammation measured by mean linear intercept, alveolar destroy index and total cell, neutrophil counts, cytokines IL-6, tumor necrosis factor (TNF)-α, CXCL1, IL-1β in bronchoalveolar lavage fluid." (PMID 32116706, 2020). "IL-1β, IL-6, IL-8, and TNFα have all been found to be elevated in COPD and in experimental settings have been found to contribute to the development of persistent airway inflammation, emphysema, and mucus production." (PMID 23533311, 2013). "Finally, the expression of major actors of cigarette smoke-induced emphysema, such as HO-1, MMP-12 and IL-1β was increased in our elastase-instilled animals, supporting the relevance of the model." (PMID 22849372, 2012). "Interestingly, we found a significant interaction between IL-1β and smoking on their effect on the odds for emphysema, with a more pronounced effect seen in never-smokers." (PMID 33936110, 2021). "On the other hand, H-EVs, but not H-MSCs, were able to reduce the neutrophil count, the mean linear intercept, and IL-1β and TGF-β levels in lung tissue, as well as reduce pulmonary arterial hypertension and increase the right ventricular area in a murine model of elastase-induced severe emphysema." (PMID 34136481, 2021). "The association between IL-1β and emphysema was more pronounced in never-smokers, emphasizing the need for PLWH without a history of smoking to be evaluated for symptoms and risk factors for emphysema, as well as PLWH with tobacco exposure." (PMID 33936110, 2021). "Moreover, the mRNA expression of other representative proinflammatory mediators, including IL-1β, tumor necrosis factor-α (TNF-α), IL-8, IL-18, and immune modulators, such as interferon regulatory factor-5 (IRF-5) and transforming growth factor-β (TGF-β), was increased in emphysema mice." (PMID 32681029, 2020). "Furthermore, RLD significantly inhibited the expressions of IL‐1β, IL‐6, TNF‐α, and TGF‐β induced by cigarette smoke exposure, reduced the number of inflammatory cells in the bronchoalveolar lavage fluid, and alleviated the severity of cigarette smoke‐induced emphysema." (PMID 28749079, 2017). "After 4 months of exposure to CS, we observed significantly increased emphysema severity (MLI and DI) and elevation of pro-inflammatory factors (TNF-α and IL-1β) in serum without a significant change in BW." (PMID 34646841, 2021). "PLWH with emphysema had higher concentrations of TNFα, IL-1β and IL-6 than PLWH without emphysema." (PMID 33936110, 2021). "PLWH with emphysema had higher concentrations of TNFα (median (IQR): 8.2 (6.4-9.8) versus 7.1 (5.7-8.6) pg/ml, p<0.001), IL-1β (median (IQR): 0.21 (0.1-0.4) versus 0.17 (0.1-0.3) pg/ml, p=0.004) and IL-6 (median (IQR): 3.6 (2.6-4.9) versus 3.1 (2.0-4.3) pg/ml, p=0.023) than PLWH without emphysema." (PMID 33936110, 2021).
gastric ulcer (66 papers, 2007 to 2025). An ulcerated lesion in the mucosal surface of the stomach. "TNF-α and IL-1β have a synergistic effect and are associated with the acute phase of inflammation and the severity of a gastric ulcer." (PMID 36836745, 2023). "Several studies show a positive correlation between the severity of gastric ulcer and the increase in pro-inflammatory cytokines (IL-1β, IL-6, and TNF-α), associated with a reduction in anti-inflammatory cytokines (IL-10), influencing inflammatory scores." (PMID 33233494, 2020). "Proinflammatory cytokines, particularly TNF-α, IL-1β and IL-6, are closely associated with the degree of mucosal damage in gastric ulcer." (PMID 32871094, 2020). "Our objective was to determine if the IL-1B -511 T>C and -31 C>T polymorphisms and H. pylori vacA genotypes are associated with risk of chronic gastritis and gastric ulcer in a Mexican population." (PMID 20979650, 2010). "In the southern Mexican population, the IL-1B -511C and -31T alleles and the -511C/-31T and -511T/-31T haplotypes are associated with increased risk of chronic gastritis and gastric ulcer." (PMID 20979650, 2010). "In the population of southern Mexico, -511C or -31T alleles and -511C/-31T or -511T/-31T haplotypes of IL-1B increase the risk of chronic gastritis and gastric ulcer." (PMID 20979650, 2010). "Similarly, oral administration of aspirin in a single dose of 200 mg/kg bw significantly increased serum TNF-α and IL-1β levels in rats with gastric ulcer caused by aspirin after 4 h of aspirin administration." (PMID 33407626, 2021). "In addition, for the role of IL-1B in adjusting a secretion of acid and protecting cell activities in gastric mucus, there is a body of research related to IL-1B polymorphism, peptic and gastric ulcer." (PMID 30320011, 2018). "Haplotypes of IL-1B SNPs and their association with gastritis and gastric ulcer." (PMID 20979650, 2010). "The objective of this study was to evaluate the relationship between IL-1B -511 T>C and -31 C>T polymorphisms and the presence of chronic gastritis and gastric ulcer, and to analyze the relationship of H. pylori vacA genotypes with gastric ulcer." (PMID 20979650, 2010). "Association of IL-1B polymorphisms with chronic gastritis and gastric ulcer." (PMID 20979650, 2010). "The impaired healing of gastric ulcer in diabetic rats was associated with suppressed tissue expression endothelial cell markers (i.e. eNOS and peNOS), enhanced pro-inflammatory reactions (i.e. IL-1β, IL-6 and myeloperoxidase activity) and reduced regenerative activity (i.e. MMP-2, IL-10 and cAMP)." (PMID 29095895, 2017). "Interestingly, in our study, the -511 TC/CC and -31 CT/TT IL-1B genotypes were associated with the presence of chronic gastritis and the presence of gastric ulcer when all cases were grouped (-511 TC/CC OR adjusted = 2.8, 95% CI = 1.6-5.1; -31 CT/TT OR adjusted = 2.9, 95% CI = 1.6-5.3)." (PMID 20979650, 2010). "Atractylodes exerts anti-inflammatory activity in gastric ulcer rats by down-regulating NF-κB and IL-1β while up-regulating IL-10 and IκBα." (PMID 41036224, 2025). "ELISA showed that the expression of IL-1β and IL-6 in the serum increased following ethanol-mediated induction of gastric ulcers, and this increase was significantly inhibited by treatment with YWS at 300 mg/kg." (PMID 39861107, 2025). "TNF-α and IL1β production are very high at the inflammatory phase of gastric ulcer which usually decreases as healing progress." (PMID 39759379, 2024). "Taken together, this study is the first to highlight the role of Apium graveolens L. in indomethacin-induced gastric ulcer, and correlate it to IKκB/NF-κB p65/IL1β, IL-6, TNF-α/iNOS signaling pathways." (PMID 38355510, 2024). "This study examines how DOP protects against gastric ulcers by looking at IL-1, IL-1β, TNF-α, and PGE2 levels." (PMID 38398633, 2024).
gastric ulcer (continued). "In an ethanol-induced gastric ulcer in vivo model, they decreased IL-1β, TNF-α, and TBARS levels by 2.1, 1.7, and 1.3 fold, respectively, in comparison to increments caused by exposure to ethanol." (PMID 38276520, 2024). "NLRP3 inflammasome is an intracellular complex associated with inflammatory response, which induces the production of mature IL-1β and triggers apoptosis through caspase-1 cleavage, playing an important role in the formation of gastric ulcer." (PMID 38807640, 2024). "The inflammatory changes that accompany gastric ulcers were investigated by exploring IL-1β expression using immunohistochemistry staining, where it was found to be increased significantly in the indomethacin group compared with the control group." (PMID 37396939, 2023). "The inflammatory response caused by gastric mucosal injury increases the expression of inflammatory cytokines including TNF-α, IL-1β, and IL-6, and further triggers neutrophil infiltration and epithelial cell apoptosis, delaying the healing of gastric ulcers." (PMID 36552666, 2022). "In the model of gastric ulcer induced by acetic acid, myrtenol treatment for 7 days also reduced mRNA levels of IL-1β and TNF-α in rats." (PMID 35712716, 2022). "Pro-inflammatory cytokines such as TNF-α and IL-1β play an important role in the pathogenesis of gastric ulcer." (PMID 34975468, 2021). "Studies have shown that pro-inflammatory cytokines, such as TNF-α, IL-1β, and IL-6 play important roles in the formation of gastric ulcers." (PMID 33233494, 2020). "Misoprostol pretreatment significantly decreased TNF-α and IL-1β contents in comparison to the gastric ulcer control group." (PMID 31731465, 2019). "Althaea officinalis pretreatment significantly decreased TNF-α and IL-1β contents in comparison to the gastric ulcer control group." (PMID 31731465, 2019). "Solanum nigrum pretreatment significantly decreased TNF-α and IL-1β contents to 37.76% and 42.53%, respectively, in comparison to the gastric ulcer control group." (PMID 31731465, 2019). "Omeprazole pretreatment significantly decreased TNF-α and IL-1β contents to 59.88% and 48.38%, respectively, in comparison to the gastric ulcer control." (PMID 31731465, 2019). "Solanum nigrum pretreatment significantly decreased TNF-α and IL-1β contents in comparison to the gastric ulcer control group." (PMID 31731465, 2019). "Misoprostol pretreatment significantly decreased TNF-α and IL-1β contents to 46.90% and 40.26%, respectively, in comparison to the gastric ulcer control group." (PMID 31731465, 2019). "This phenomenon was initiated via the NF-κB pathway where the production of proinflammatory cytokines TNF-α and IL-1β, upregulation of iNOS gene expression, and release of NO were enhanced by activated NF-κB during gastric ulcer formation." (PMID 30116487, 2018). "Inevitably, alcohol resulted in the augmentation of the proinflammatory cytokines: TNF-α participating in gastric ulcer via boosting apoptosis, NF-κB, iNOS, and neutrophil infiltration and IL-1β arousing the oxidative stress inflicting the gastric damage." (PMID 30116487, 2018). "The pro-inflammatory cytokines TNF-α and IL-1β have been shown to play an important role in the pathogenesis of gastric ulcer by initiating an early inflammatory process, while the regulatory cytokine IL-10 is known to attenuate TNF-α production." (PMID 23484048, 2013). "Accordingly, oral TA treatment of mice with ethanol-induced and ethanol/HCl-induced gastric ulcers exhibited gastroprotective effects, which were associated with a decrease in TNF-α, IL-1β and IL-6 protein levels and an increase in IL-10 protein levels in gastric tissue." (PMID 40427543, 2025).
gastric ulcer (continued). "In addition, it was reported that the anti-inflammatory effect of pioglitazone against gastric ulcer was through decreasing IL-1β, TNF-α and NO levels." (PMID 38441571, 2024). "Having confirmed that numerous biological agents able to diminish the levels of pro-inflammatory cytokines such as TNF-α, IL-1β, and IL-6, could potentially exhibit effectiveness in the management of gastric ulceration." (PMID 38355510, 2024). "During ethanol-induced gastric ulcer formation, NF-κB governs the increased transcription of genes encoding inducible nitric oxide synthase (iNOS), COX-2, and inflammatory cytokines including tumor necrosis factor-α (TNF-α), interleukin (IL)-6, and IL-1β." (PMID 34630623, 2021). "Then we evaluated the levels of the mayor inflammatory cytokines responsible for driving the inflammatory response in gastric ulcer such as IL-1β, IL-6 and TNF-α40." (PMID 33574472, 2021). "Previous research showed that gastric ulcers caused by ethanol may activate the innate immune system and upregulate the levels of proinflammatory cytokines, such as TNF-α, IL-1β, and IL-6." (PMID 34580595, 2021). "Pretreatment with AAEs significantly reduced the proinflammatory cytokine levels of IL-1β and IL-6 and enhanced the anti-inflammatory cytokine IL-10 in the gastric ulcer mice, suggesting that they provide protection against the inflammation of gastric ulcer." (PMID 34580595, 2021). "Additionally, Althaea officinalis pretreatment significantly decreased TNF-α and IL-1β contents to 30.38% and 34.42%, respectively, in comparison to the gastric ulcer control group." (PMID 31731465, 2019). "Furthermore, ethanol provoked the gene expression of TNF-α, IL-1β, and iNOS, inflicting the immense effect of the generated NO on gastric ulcer formation." (PMID 30116487, 2018). "We did not observe significant association between infection with H. pylori vacA s1 with chronic gastritis or gastric ulcer in carriers of the IL-1B-511C and -31T alleles or their haplotypes (data not shown)." (PMID 20979650, 2010). "The IL-1B -511C/-31T haplotype was associated with chronic gastritis (OR = 2.1, 95% CI = 1.2-3.8) but not with gastric ulcer." (PMID 20979650, 2010). "Therefore, by reducing TNF-α, IL-6, and IL-1β expression, A. graveolens may be considered as an alternative agent for treating gastric ulcer patients." (PMID 38355510, 2024). "Compared with the control group, the expression levels of IL-1β, IL-6, and TNF-α in the gastric tissues of rats in the model group were significantly higher (p < 0.01), suggesting that the increased levels of inflammatory cytokines (IL-1β, IL-6, and TNF-α) were associated with gastric ulcers." (PMID 38398633, 2024). "FCPP aqueous extract might prevent gastric ulcers by inhibiting the phosphorylation of IκBα and the activation of the NF-κB pathway, thereby further regulating the decrease of the expression levels of caspase-1 and IL-1β, and inhibiting inflammation." (PMID 37372566, 2023). "For example, studies showed that Dioscorea administration in ethanol-induced gastric ulcer models significantly increased the activity of antioxidant enzymes such as SOD, GPx, and CAT, while reducing pro-inflammatory cytokines like TNF-α, IL-1β, and IL-6." (PMID 41010469, 2025). "Moreover, gastric ulcer indices, histopathological morphology, oxidative stress markers (MDA, GSH, SOD), inflammatory mediators (NO, PGE2), and cytokine gene expression (TNF-α, IL-6, IL-1β, iNOS) were evaluated via enzyme-linked immunosorbent assay (ELISA) and quantitative real-time PCR." (PMID 40361682, 2025). "In ethanol-induced gastric ulcers, CPC down-regulates the expression of NFκB and inflammatory cytokines such as IL-1β and TNF-α." (PMID 39000141, 2024). "In gastric ulcer models, honey reduced the gastric mucosal malondialdehyde (MDA), IL-1β, IL-6, and TNF-α." (PMID 38045104, 2023).